COMT (catechol-O-methyltransferase)
Diseases named in the same sentence as COMT in open-access papers (continued):
Sharing a sentence is not in itself a finding about the gene and the disease.
schizophrenia (continued). "We performed a case-control study by genotyping analysis using 360 cases and 348 controls in Korean subjects to determine the association between functional polymorphisms in COMT and MTHFR and schizophrenia risk." (PMID 21217836, 2010). "In the present study, we examined the relationship between functional polymorphisms in COMT and MTHFR polymorphisms and schizophrenia risk." (PMID 21217836, 2010). "Genetic epigenetic gene expression results showed that dopamine degradation in the synaptic cleft is increased in individuals with schizophrenia because of increased COMT activity or expression." (PMID 21358990, 2010). "The genotypic distributions of the three genotypes in the COMT genes are as follows: healthy controls, Met/Met 5 (8.3%), Val/Met 25 (41.7%), Val/Val 30 (50.0%); patients with schizophrenia, Met/Met 4 (8.9%), Val/Met 21(46.7%), Val/Val 20 (44.4%)." (PMID 19424500, 2009). "In conclusion, an implication of the impact of the COMT genotype on prefrontal cortical function in patients with schizophrenia was also identified by noninvasive and less-demanding NIRS measurement." (PMID 19424500, 2009). "In previous fMRI and PET studies that employed the n-back task, a significant effect of the COMT genotype in patients with schizophrenia was reported in the dorsolateral and ventrolateral PFC." (PMID 19424500, 2009). "The explained PPI variance by COMT genotype for the males in our study was 13%, which is situated between the effect in Roussos male sample (25%) and our mixed-sex schizophrenia sample (9%)." (PMID 19545856, 2009). "Studies have shown that schizophrenia patients have increased levels of the COMT gene in glial cells located in the frontal cortex." (PMID 19445674, 2009). "This study not only replicated the effect of COMT on prefrontal cognitive function in schizophrenia, but also showed the usefulness of NIRS in future translational research on psychiatric neuroimaging." (PMID 19424500, 2009). "In this study, the prominent impact of the COMT in patients with schizophrenia was found in the frontopolar PFC, whereas there was also a significant trend (uncorrected p<0.01) in the dorsolateral and ventrolateral PFC." (PMID 19424500, 2009). "In the same direction association studies have reported several genes of this region associated with risk to develop schizophrenia and bipolar disorder, including PRODH, COMT, ZNF74, PCQAP, UFD1L, ZDHHC8, DGCR2 and SNAP29." (PMID 18284679, 2008). "In this study we have examined the expression of COMT in post mortem cerebellum tissue from individuals diagnosed with schizophrenia, bipolar disorder, and depression." (PMID 16483362, 2006). "To conclude, we have examined the role of COMT expression in the aetiology of schizophrenia, depression, and bipolar disorder." (PMID 16483362, 2006). "Future studies in larger independent samples investigating joint interactions with other candidate dopamine system genes (e.g. dopamine transporter gene [DAT1]) and COMT gene on schizophrenia endophenotypes are warranted." (PMID 17173666, 2006). "In this study we have investigated the role of COMT expression in the development of schizophrenia and two aetiologically-related psychiatric disorders: bipolar affective disorder and depression." (PMID 16483362, 2006). "Taken together, current evidence suggests that COMT variants may provide a weak predisposition to a variety of psychiatric conditions via alteration of dopamine levels in the prefrontal cortex (supported by the association of the same haplotype with both, schizophrenia and bipolar disorder)." (PMID 16232322, 2005). "Reduced COMT activity results in elevated dopamine levels, which may disrupt normal neurotransmission and contribute to schizophrenia pathophysiology, potentially exacerbating symptoms associated with the disorder." (PMID 40779062, 2026).
schizophrenia (continued). "Expanding the analysis to include additional schizophrenia-associated genes such as DISC1, NRG1, COMT, and DTNBP1 could provide a more comprehensive view of the genetic risk factors relevant to our population." (PMID 40977746, 2025). "Epigenetic changes have been well-established in BDNF, COMT, FKBP5, NR3C1, SLC6A4, and DRD2, genes associated with psychiatric disorders, including schizophrenia, major depressive disorder (MDD), bipolar disorder (BP), post-traumatic stress disorder (PTSD), and autism spectrum disorder (ASD)." (PMID 41234420, 2025). "It has also been reported that patients with refractory epilepsy who carried the catechol-O-methyltransferase (COMT) Val (rs4680) allele had more severe symptoms of schizophrenia (p = 0.007) on the personality assessment inventory than non-carriers." (PMID 39858450, 2025). "COMT is an enzyme that plays a crucial role in the metabolism of neurotransmitters, including dopamine, norepinephrine, and epinephrine, and has often been suggested as a famous candidate gene in the development of schizophrenia." (PMID 39457610, 2024). "Moreover, COMT Val158Met (rs4680) was related to treatment response and treatment resistance in patients suffering from schizophrenia." (PMID 39062492, 2024). "In line with our result, the rs1801133 A allele was also found to attenuate the negative effect of COMT Val homozygosity on IQ in patients with schizophrenia." (PMID 39203776, 2024). "Notably, low COMT methylation has also been detected in saliva samples from schizophrenia and bipolar disorder patients, suggesting potential cross-tissue relevance and supporting the development of non-invasive biomarkers." (PMID 39678047, 2024). "We therefore investigated whether miR-34a-5p also targets COMT, given its importance in studies of schizophrenia patients." (PMID 38427212, 2024). "Also, candidate gene studies have reported associations between schizophrenia and THRB, COMT, DIXDC1, and WBP1L." (PMID 38503926, 2024). "Therefore, the interaction between COMT and PRODH genes can cause an augmentation in dopamine activity, predisposing the patient to psychosis and schizophrenia." (PMID 38392589, 2024). "A functional polymorphism in the catechol-O methyltransferase (COMT) gene was associated with reduced dopamine function in the prefrontal cortex and moderated the influence of substance use, and the COMT gene has been suggested in the pathogenesis of schizophrenia." (PMID 38814466, 2024). "The less-studied COMT rs174696 and SLC6A3 (DAT1) rs464049 appear to interactively influence the risk of schizophrenia, but their functionality is yet unknown." (PMID 39595853, 2024). "Importantly, in patients with schizophrenia, COMT DNA methylation was inversely correlated with depressed subdomain of the PANSS, i.e., the higher the depressive symptoms, the lower the DNA methylation." (PMID 37510262, 2023). "Our results have shown a significant genotypic and haplotypic association of COMT rs4680 and rs4818 gene polymorphisms with particular clinical symptoms evaluated by the individual PANSS subscales scores in male and female patients with schizophrenia." (PMID 37510262, 2023). "In addition, it would be interesting to explore how different COMT genotypes and their haplotype combinations relate to psychopathology in different stages throughout the course of schizophrenia in male and female participants." (PMID 37510262, 2023). "Variants of the catechol-O-methyltransferase (COMT) gene, which represents a key regulator of dopaminergic neurotransmission and possibly a pharmacological target, has also been considered as a genetic predisposition factor to OCS in schizophrenia." (PMID 37627285, 2023). "In particular, the difference in the rules of allele interactions between patients with schizophrenia and controls was revealed when the effects exerted on PPI by polymorphism rs4680 in the COMT gene, as well as polymorphisms rs1051730 and rs1317286 in the CHRNA3 gene, were estimated." (PMID 35846783, 2022).
schizophrenia (continued). "Therefore, further investigations on COMT, RASSF1 and GPM6A on larger population are warranted to validate our findings and further elucidate the association between schizophrenia and variations in these genes." (PMID 35528814, 2022). "However, the interaction of COMT Val158Met (rs4680) and sex on the clinical characteristics and cognitive performance in patients with schizophrenia is unclear." (PMID 36203835, 2022). "Nonetheless, a haplotype of the COMT rs4818 and rs740603 polymorphisms was reported to be linked to negative symptoms of schizophrenia." (PMID 34287249, 2021). "COMT enzyme takes part in the dopamine degradation pathway and plays a vital role in schizophrenia." (PMID 34725583, 2021). "In addition, our results extend the preliminary knowledge on the treatment potential of MAO-B and COMT inhibitors on specific symptoms of schizophrenia." (PMID 34287249, 2021). "COMT is a prime candidate for ameliorating the cognitive dysfunction of schizophrenia." (PMID 33315097, 2021). "Apart from MMP9, hypomethylations have also been detected in other genes, such as AluY A3 CpG, promoter of GRIN2B, CpG2 and CpG3 in TREM2 intron 1, CpG sites in FAM63B and intergenic region on chromosome 16, CpG sites in TBC1D22A, and COMT in schizophrenia compared with controls." (PMID 34366776, 2021). "Additionally, the study confirmed more significant interactive effects of genotypes of COMT and IL-10 on cognition in schizophrenia patients than in controls." (PMID 34725583, 2021). "Our findings suggest that higher dopamine degradation, related to COMT rs4680 and rs4818 variants, is associated with a sex-specific increase in severity of negative symptoms in schizophrenia patients." (PMID 34287249, 2021). "•Schizophrenia probands and relatives displayed reduced P3 varying by COMT genotype." (PMID 32950905, 2020). "Similar to our findings regarding COMT, the Ala72Ser (rs6267) variant has been consistently reported to be associated with a sex-specific increased risk of schizophrenia and the effects of treatment on negative symptoms." (PMID 32664413, 2020). "COMT-Val158Met genotype (COMT genotype from here forward for simplicity) has also been shown to influence structural and functional aspects of auditory processing, including dopaminergic alterations in both healthy subjects and patients with schizophrenia." (PMID 30712251, 2020). "Finally, we provide novel evidence that COMT variation differentially impacts neural functions in individuals with genetic liability for schizophrenia versus bipolar disorder." (PMID 32950905, 2020). "In this context, our present findings of differential effects of COMT variation on neural functions related to higher-order processing in individuals with liability for schizophrenia and bipolar disorder are interesting, though must be interpreted with caution." (PMID 32950905, 2020). "COMT polymorphisms are also related to self-reported anhedonia in relatives of patients with schizophrenia, but not relatives of bipolar disorder patients suggesting differences in genetic liability for the two disorders." (PMID 32950905, 2020). "To restrict analyses, we only examined the associations between COMT and N2 in relation to schizophrenia given the lack of group differences in the bipolar disorder-related samples; these analyses failed to yield any effects involving genotype." (PMID 32950905, 2020). "In the same cohort of patients, the authors also found that the neuregulin-1 (NRG1) rs35753505 polymorphism, which has been studied extensively for its potential role in the pathogenesis of schizophrenia, further decreased auditory hallucinations when present with COMT Val/Val." (PMID 32742620, 2019). "In a study examining the expression levels of COMT mRNA in post mortem cerebellum samples derived from psychiatric patients, including those with schizophrenia, the authors failed at identifying differences in COMT expression or methylation in any psychiatric disorder." (PMID 31557839, 2019).
schizophrenia (continued). "Gender differences were previously noticed in COMT activity as well as in distribution of the COMT rs4680 genotypes in healthy individuals and patients with schizophrenia." (PMID 30018555, 2018). "In conclusion, this result supports the hypothesis that variations in DAOA and COMT genes may play a role in schizophrenia and bipolar disorder." (PMID 30719257, 2018). "Haplotype including COMT rs4818 G allele (with rs740603/G allele) was linked to negative symptoms of schizophrenia." (PMID 30018555, 2018). "Like COMT, the GAD1gene that encodes GAD67 is a hypothesis-driven gene-candidate for the risk of schizophrenia." (PMID 29429137, 2018). "The presence of one or two A allele in the COMT rs4680 elevated the risk of violence in male, but not female patients with schizophrenia." (PMID 30018555, 2018). "Overall, these data suggest how COMT genotype could provide useful information in the selection of an appropriate and personalized pharmacological and rehabilitative treatment in schizophrenia." (PMID 30687100, 2018). "Therefore, investigation of the genotypic and haplotypic association between COMT SNPs rs4680 and rs4818 and TRS in the larger sample of females with schizophrenia is warranted." (PMID 30018555, 2018). "MAOA mRNA was significantly increased by 45% in the substantia nigra in schizophrenia cases compared with controls (F=6.34, df=56, P=0.015), but no diagnostic changes were found in the levels of MAOB mRNA (F=0.81, df=53, P=0.372) or COMT mRNA (U=462, z=0.89, P=0.371)." (PMID 28094812, 2017). "In addition, the hypomethylation of the COMT gene promoter, which leads to over-expression of COMT, has been found in post-mortem brains, as well as in peripheral blood cells of schizophrenia patients." (PMID 28358316, 2017). "COMT inhibition is a means of treating Parkinson’s disease, schizophrenia and depression." (PMID 27981425, 2017). "The Val/Val genotype of this polymorphism, which results in the higher COMT activity compared to Met/Met genotype, may lead to a decreased DA neurotransmission in PFC, characteristic for schizophrenia." (PMID 28358316, 2017). "For example 25–30% of adult patients with 22q11.2 deletion syndrome (DiGeorge Syndrome), a deletion which includes the COMT gene – of relevance for dopamine metabolism – suffer from schizophrenia, making this one of the highest-penetrance genetic changes involved in schizophrenia to date." (PMID 27450778, 2016). "The sex-specific association of the COMT gene with the negative dimension of psychosis proneness described here is in line with several studies in schizophrenia (reviewed by Godar and Bortolato)." (PMID 25722988, 2015). "Specifically, membrane-bound catechol-O-methyltransferase (MBCOMT) is an integral membrane protein that catalyzes the methylation of catechol substrates and has been linked to several diseases such as Parkinson’s disease and Schizophrenia." (PMID 26246150, 2015). "We have reanalyzed the association between COMT, ERBB4 or NRG1 and EEM in schizophrenia." (PMID 26242244, 2015). "The finding of an association between the COMT polymorphism and the negative dimension of the psychosis proneness phenotype provides evidence that the biological effects of the COMT gene may be relevant to the pathophysiology of schizophrenia." (PMID 25722988, 2015). "Candidate gene studies have identified a number of genes, such as catechol-O-methyltransferase (COMT), brain-derived neurotrophic factor (BDNF), neuregulin-1 (NRG-1), and disrupted in schizophrenia (DISC-1) that appear to be shared risk factors for schizophrenia, bipolar disorder, and MDD." (PMID 25202283, 2014). "The genotypic distributions of three genotypes in the COMT gene were as follows: healthy controls, val/val, n = 68 (45.6%), val/met, n = 62 (41.6%), and met/met, n = 19 (12.8%); and patients with schizophrenia, val/val, n = 68 (47.5%), val/met, n = 62 (39.8%), and met/met, n = 19 (12.7%)." (PMID 24282499, 2013).
schizophrenia (continued). "Multivariate analysis showed that the COMT Val108/158Met polymorphism has no influence in the clinical symptomatology of schizophrenia." (PMID 23184041, 2013). "In this study, we investigated whether the COMT Val158Met polymorphism affected cognitive function assessed by the BACS-J in healthy controls and in patients with schizophrenia." (PMID 24282499, 2013). "We determined the relation of the COMT Val108/158Met polymorphism with schizophrenia or its symptomatology (negative, disorganized and psychotic dimension)." (PMID 23184041, 2013). "More studies have reported that the val genotypes of the COMT Val158Met polymorphism have a negative effect on cognitive tasks that engage executive function in patients with schizophrenia." (PMID 24282499, 2013). "Previous studies have suggested a relationship between the COMT Val108/158Met polymorphism and positive or negative symptoms in schizophrenia." (PMID 23184041, 2013). "In conclusion, our results suggest that the functional Val108/158Met polymorphism of the COMT gene exhibited a lack of association between this polymorphism and schizophrenia in a sample of Mexican schizophrenic patients." (PMID 23184041, 2013). "Our results showed a relatively weak association between executive function within the six cognitive domains and COMT Val158Met polymorphism in the healthy controls but not in the patients with schizophrenia." (PMID 24282499, 2013). "Moreover, this module was found to contain two genes previously suggested to be involved in schizophrenia; namely Catechol-O-methyltransferase (COMT) and phosphatidyl-inositol-4-kinase-catalytic-a (PIK4CA)." (PMID 22761806, 2012). "We identified decreased expression of several genes (among which COMT, Ufd1L, PCQAP, and GNB1L) previously linked to schizophrenia as well as involvement of signaling pathways relevant to schizophrenia, of which Neurotrophin/Trk and neuregulin signaling seems to be especially notable." (PMID 22457764, 2012). "However, this particular SNP's effect on the risk to be affected by schizophrenia, a disorder that also features reduced brain GABA levels, seems to depend on the COMT promoter polymorphism rs2075507, so that epistasis seems to play an important role." (PMID 22662185, 2012). "Recently, studies indicated that three COMT SNPs (rs2020917, rs737865 and rs5993883) may be the risky genetic factors of schizophrenia." (PMID 23209597, 2012). "Further, there is evidence to suggest that the presence of the Met allele in the catechol-O-methyltransferase (COMT) Val158Met polymorphism, which has recently been put forth as an important neurobiological risk factor for violence in schizophrenia, increases violence risk solely in men." (PMID 22359622, 2012). "Despite the overlap of COMT and AKT1 in associations with cancer and schizophrenia, molecular and cell biological interactions of COMT and AKT1 have not been explored." (PMID 20520724, 2010). "Since COMT, AKT1, and ErbB-signaling are each implicated in both cancer and schizophrenia, NRG1-ErbB signaling in B lymphoblasts provides a biologically plausible research tool for elucidating cellular mechanisms relevant to both cancer biology and neurobiology." (PMID 20520724, 2010). "Finally, we also carried out an association analysis on the effect of two genetic variants of enzymes of the methylation pathway, the COMT Val158Met and MTHFR C677T polymorphisms, on schizophrenia risk." (PMID 21217836, 2010). "Interestingly, both COMT and AKT1 have also been implicated in the pathogenesis of cancer and schizophrenia, and their associations with these disease conditions have been extensively studied." (PMID 20520724, 2010). "Our findings implicate genetic and functional interactions between COMT and AKT1 and may provide novel insights into pathogenesis of schizophrenia and other ErbB-associated human diseases such as cancer." (PMID 20520724, 2010).